BCL2 (BCL2 apoptosis regulator)
Diseases named in the same sentence as BCL2 in open-access papers (continued):
Sharing a sentence is not in itself a finding about the gene and the disease.
head and neck cancer (25 papers, 2005 to 2025). A primary or metastatic malignant neoplasm affecting the head and neck. "We have recently shown that tumor-associated endothelial cells exhibit significantly higher Bcl-2 expression that is directly correlated with metastatic status of head and neck cancer patients." (PMID 26509633, 2015). "Overexpression of anti-apoptotic Bcl-2 protein in head and neck cancer cells has been linked to increased resistance to radio- and chemotherapy and is considered a viable therapeutic target." (PMID 25229941, 2014). "Indeed, a recent publication has shown that NPC, an epithelial head and neck cancer associated with EBV that expresses high levels of BCL‐2 in 80% of cases, can be efficiently treated by a combination of ABT‐199 and S63845, an MCL‐1 inhibitor." (PMID 32623836, 2020). "MSNs with curcumin (Cur-MSNs) have previously shown selective cytotoxicity against HN5 head and neck cancer cells by lowering Bcl-2 expression, increasing the Bax/Bcl-2 ratio, and inducing ROS-mediated apoptosis." (PMID 40688030, 2025). "As demonstrated in several studies, the intricate interplay and balance between BAX and BCL-2 is critical in regulating apoptosis and plays a pivotal role in the pathophysiology of head and neck cancer." (PMID 39966442, 2025). "For instance, the Bcl-2/Bax ratio was significantly associated with both the absolute number and the rate of CD4(+) T cells and natural killer cell activity in head and neck cancer patients." (PMID 33622179, 2021). "In summary, these data suggest that the expression of Cx43 and Bcl-2 are inversely correlated in head and neck cancer cell lines and tissue samples as well." (PMID 31766723, 2019). "A recent study in head and neck carcinoma showed that cancer cells bound to Bcl-2 overexpressing ECs (EC-Bcl-2) via E-selectin presented significantly higher anoikis resistance." (PMID 31885581, 2019). "We have recently shown that La protects head and neck cancer cell line SCC 22B against cisplatin-induced cell death by maintaining Bcl2 protein synthesis." (PMID 28291789, 2017). "We have shown that C2.01 impairs binding of La to specific mRNAs in cells and thereby mimics the effect of La depletion in head and neck cancer cells by reducing Bcl2 protein expression and sensitization to cisplatin." (PMID 28291789, 2017). "A previous study also showed that TEC with Bcl-2 overexpression in head and neck cancer patients promoted tumor cell proliferation and invasion by paracrine IL-8." (PMID 27121053, 2016). "In this study, we have demonstrated the presence of Bcl-2 positive CECs in the blood samples from head and neck cancer patients." (PMID 26509633, 2015). "In contrast, CECs from head and neck cancer patients showed marked increase in Bcl-2 levels as compared to CECs from healthy volunteers." (PMID 26509633, 2015). "We have previously demonstrated that tumor samples from head and neck cancer patients have significantly higher Bcl-2 positive tumor vessels as compared to matched normal controls." (PMID 26509633, 2015). "Results obtained from this study also demonstrate that blood samples from head and neck cancer patients contain significantly higher Bcl-2 positive (activated) circulating endothelial cells as compared to healthy volunteers." (PMID 26509633, 2015). "Our results demonstrate that blood samples from head and neck cancer patients contain significantly higher Bcl-2-positive CECs as compared to healthy volunteers." (PMID 26509633, 2015). "In this study, we further examined if blood samples from head and neck cancer patients also contained elevated levels of Bcl-2 positive CECs." (PMID 26509633, 2015). "In comparison, Bcl-2 is a pro-survival protein that is over-expressed in multiple human cancer cells including head and neck cancer, which prevents cancer cell death." (PMID 25229941, 2014).
head and neck cancer (continued). "Here, we found that inhibition of EGFR by erlotinib results in phosphorylation of STAT3 at Tyr705 leading to its activation and to increased levels of Bcl2/Bcl-XL at both mRNA and protein levels in head and neck cancer cells." (PMID 24019973, 2013). "In addition BCL2 over-expression in response to cigarette smoke has also been reported in an earlier study in the context of head and neck cancer." (PMID 24586750, 2014). "Antisense oligodeoxynucleotides (ASODN) and short interfering RNA (siRNA) molecules have been used to silence the expression of anti-apoptotic Bcl-2 protein in head and neck cancer cells, which proved to successfully induce cancer cell death in response to chemotherapy both in vitro and in vivo." (PMID 25229941, 2014). "Intriguingly, specific knockdown of PTPMeg2 also activated the STAT3/Bcl2/Bcl-XL survival pathway, suggesting that PTPMeg2 may play an important role in regulating the sensitivity of erlotinib to head and neck cancer cells." (PMID 24019973, 2013). "Importantly, specific knockdown of PTPMeg2 also led to increased STAT3 phosphorylation and elevated levels of Bcl2 and Bcl-XL in head and neck cancer cells, which further supports the role of PTPMeg2 as a physiologic STAT3 phosphatase, as recently reported." (PMID 24019973, 2013). "In summary, the present studies have demonstrated that inhibition of EGFR by erlotinib stimulates phosphorylation and activation of STAT3 leading to increased levels of Bcl2 and Bcl-XL, which could reduce the efficacy of erlotinib against head and neck cancer." (PMID 24019973, 2013). "Silencing of STAT3 not only downregulates Bcl2 and Bcl-XL but also significantly sensitizes head and neck cancer cells to erlotinib, suggesting that targeting STAT3 may have great potential to improve the efficacy of erlotinib against head and neck cancer." (PMID 24019973, 2013). "By studying a homogeneous group of head and neck cancer, using a strict definition of radioresistance to avoid confounding factors, we have demonstrated that expression of antiapoptotic members, bcl-2 and bcl-XL, and underexpression of proapoptotic marker, bax, are associated with radioresistance." (PMID 15928664, 2005). "Here, we found that inhibition of EGFR by erlotinib stimulated phosphorylation and activation of STAT3 leading to increased Bcl2/Bcl-XL expression in head and neck cancer cells, which may dampen the therapeutic efficacy of erlotinib against head and neck cancer." (PMID 24019973, 2013). "In vitro and in vivo studies have shown that the combination of curcumin and resveratrol enhances the apoptotic effects of head and neck cancer cells, including upregulation of PARP-1 cleavage and the Bax/Bcl-2 ratio and downregulation of ERK1 and ERK2 phosphorylation." (PMID 36193082, 2022). "In vitro studies showed that EGCG inhibited cisplatin-induced ROS, ERK1/2 and STAT1 activation in UMSCC head and neck cancer cells, but had little effect on cisplatin-induced inhibition of STAT3, Bcl-2 and Bcl-xL levels or the observed increases in cleaved caspase-3." (PMID 28703809, 2017).
cerebral infarction (24 papers, 2011 to 2024). An ischemic condition of the brain, producing a persistent focal neurological deficit in the area of distribution of the cerebral arteries. "Reducing neuronal apoptosis by upregulation of the ratio of Bcl-2/Bax is conducive to the recovery of neural functions after cerebral infarction." (PMID 36817860, 2023). "It has been suggested that increased expression of Bcl-2 in the brain reduces the size of cerebral infarct lesions and has a protective effect on neurons." (PMID 36297399, 2022). "MiR-130a alleviated neuronal apoptosis and changes in the expression of Bcl-2/Bax and caspase-3 in cerebral infarction rats through the PI3K/AKT signaling pathway." (PMID 36547905, 2022). "Results revealed that expression of the GRP78 and Bcl-2 proteins decreased in the cerebral infarction cortex of MCAO rats." (PMID 33820869, 2021). "SB+I-FA consequently suppressed p90RSK/Bad/CREB/Bcl-2 signaling and triggered the Bax-mediated caspase-3-dependent apoptotic pathway in the cortical penumbra, leading to increased cerebral infarction 7 d after reperfusion." (PMID 27187745, 2016). "As miR-497 directly binds to the 30-UTR of Bcl-2/-w, the knockdown of cerebral miR-497 in mice enhanced Bcl-2/-w protein levels in the ischemic region, attenuated brain infarction, and improved neurological outcome after focal ischemia." (PMID 23365789, 2013). "Results showed that DSCXQ intervention significantly reduced cerebral infarct size, ameliorated behavioral abnormality, inhibited the expression of Sphk1, S1PR1, CD62P, Bax, Cleaved Caspase-3, while increased the level of Bcl-2, and prevented neuronal apoptosis." (PMID 34026822, 2021).
cholangiocarcinoma (24 papers, 2007 to 2026). A carcinoma that arises from the intrahepatic biliary tree (intrahepatic cholangiocarcinoma) or from the junction, or adjacent to the junction, of the right and left hepatic ducts (hilar cholangiocarcinoma). "For instance, miR-320 was reported downregulated in malignant cholangiocarcinoma, which subsequently was found to negatively regulate Mcl-1 or Bcl-2 (anti-apoptotic molecules) expression; in turn associated with chemotherapeutic drug-triggered apoptosis." (PMID 27119506, 2016). "Bcl-2 family (Bcl-xL, Bcl-2, Mcl-1) are vital members of anti-apoptotic proteins that regulate of the apoptotic pathway, and they have been reported to over-express in cholangiocarcinoma." (PMID 31391034, 2019). "The current work was performed to evaluate if high Stathmin expression would regulate anti-apoptotic signaling by enhancing the Bax/Bcl-2 ratio; critical to cholangiocarcinoma cell survival." (PMID 28178656, 2017). "Furthermore, Tan-IIA upregulated the level of cleaved caspase-3 and suppressed the expression of Bcl2, which ultimately induced apoptosis of Cholangiocarcinoma cells." (PMID 34588580, 2021). "extended the apoptotic activity of USP8 in cholangiocarcinoma cells, where the silencing of USP8 was reported to decrease Bcl-2 expression and increase Bax, cleaved Caspase 3, and cleaved Caspase 9 expression and thereby triggering apoptosis." (PMID 36338727, 2022). "Therefore, according to the effects of fucoidan in the up-regulation of Bax, cleaved caspase-3, and cleaved PARP, down-regulation of Bcl-2, and alteration of ΔΨm, it could be implied that fucoidan has potential in apoptotic induction via an intrinsic pathway on CL-6 cholangiocarcinoma cell." (PMID 33507701, 2021). "ABC294640 synergized with Bcl-2/Bcl-xL inhibitors ABT-263 and Obatoclax to induce cholangiocarcinoma cell death." (PMID 32722626, 2020). "Treatment with a Bcl-2-specific BH3 mimetic, ABT-199, reduced tumor formation and tumor burden in a murine model of cholangiocarcinoma." (PMID 24973208, 2014). "As anticipated, the results demonstrated a downregulation of Bcl-2 and Survivin, along with an upregulation of caspase-3 upon EIF3B knockdown, implying that EIF3B might be involved in cholangiocarcinoma cell apoptosis through regulating these proteins." (PMID 38687509, 2024). "Altough human cholangiocarcinoma do not express the protooncogene Bcl-2, other antiapoptotic proteins of the Bcl family such as Mcl-1 and Bcl-xl are expressed." (PMID 18154639, 2007). "However, based on our RNA-seq data, the KAT2B/GLI1/BCL2 pathway is not applicable in cholangiocarcinoma." (PMID 38641672, 2024).
gastric adenocarcinoma (24 papers, 2012 to 2025). "In silico analysis showed that BCL2 3’UTR contains a functional miR-204-binding site and an experiment with mutated BCL2 3’UTR showed confirmed that miR-204 targets Bcl-2 and its downregulation results in aberrant Bcl-2 expression in a gastric adenocarcinoma cell line." (PMID 29382303, 2018). "Bcl-2, an significant anti-apoptosis regulator located at chromosome 18q21 and encoding a 26-kDa protein localized mainly in the mitochondrial membrane, is overexpressed in gastric adenocarcinoma." (PMID 24260067, 2013). "Highly concentrated calprotectin is cytotoxic and can induce apoptosis in AGS cell lines, the common type of gastric adenocarcinoma cell line, due to its effect on the Bax/Bcl-2 expression ratio and ability to inhibit ERK activation." (PMID 41164825, 2025). "Decreased Bcl-2 gene expression signified atrophic gastritis and IM in presence of cancer, as well as intestinal type gastric adenocarcinoma." (PMID 28662697, 2017). "The increase in COX-2 activity in gastric adenocarcinoma has been related to bcl-2 expression and an increase in cell survival." (PMID 29207960, 2017). "With regard to gastric adenocarcinoma, double immunostaining analyses of the present study demonstrated colocalization of Beclin 1 and Bcl-2-positive immunoreactivity in human gastric adenocarcinoma." (PMID 24527069, 2014). "When gastric adenocarcinoma cells were dual-labeled with these two antibodies, Bcl-2 immunoreactivity colocalized with Beclin 1 immunoreactivity in poorly differentiated human gastric adenocarcinoma." (PMID 24527069, 2014). "In terms of mechanism, a study with fucoidan, demonstrated its cytotoxic effect on gastric adenocarcinoma cell cultures by inducing apoptosis, which was mediated by a decrease in the expression of antiapoptotic genes, such as Bcl-2 and Bcl-xL, in addition to activation of caspases." (PMID 41150200, 2025). "In AGS human gastric adenocarcinoma cells, crocetin treatment induced accumulation of cells in sub G1 phase, mitochondrial apoptosis and caspases signaling activation, Bax up-regulation and Bcl-2 down-regulation." (PMID 35267408, 2022). "In AGC human gastric adenocarcinoma, phytol induced apoptosis, which was evidenced by accumulated cell population in the sub-G1 phase, down-regulation of Bcl-2, overexpression of Bax and eventually the activation of caspase 9 and 3, and PARP cleavage through mitochondrial depolarization." (PMID 35267408, 2022). "Notably, confocal laser microscope data indicated co-expression of Bcl-2 and Beclin 1 in poorly differentiated human gastric adenocarcinoma." (PMID 24527069, 2014). "In order for miR-449a to downregulate Bcl-2 expression, we hypothesize that miR-449a may induce gastric adenocarcinoma cell apoptosis." (PMID 24260067, 2013). "The down-regulation of Bcl-2 and up-regulation of Bax, Caspase-9, and Caspase-3 protein expression in cancerous cells may draw attention to thymol as a potential candidate for the development of future gastric adenocarcinomas treatment strategies." (PMID 32709059, 2020). "In the context of the present study, we hypothesize that Bcl-2/Beclin 1 signaling may be a critical regulator of the biological effects of gastric adenocarcinoma and may be a key signaling element for the autophagic process, reflecting the prognostic result of patients." (PMID 24527069, 2014). "Furthermore, we hypothesize that increased Bcl-2/Beclin 1 signaling in human gastric adenocarcinoma may contribute to the interplay of apoptotic and autophagic events." (PMID 24527069, 2014). "Bcl-2, BH3 interacting domain death agonist (Bid), and Bax increased in Helicobacter-infected gastric adenocarcinoma." (PMID 40264171, 2025).
gastric adenocarcinoma (continued). "In an in vitro experimental settings, phytol has been demonstrated to induce apoptosis in human gastric adenocarcinoma AGS cells, downregulates Bcl-2, upregulates Bax, activates caspase-9 and -3 and induces PARP cleavage." (PMID 30100991, 2018). "Crocetin administration to 1-methyl-3-nitro-1-nitrosoguanidine (MNNG)-induced gastric adenocarcinoma (AGS) rats inhibited proliferation, induced apoptosis, suppressed Bcl-2, and increased regulation of Bax gene expression as well as increasing lactate dehydrogenase and anti-oxidant agent activity." (PMID 38419885, 2024). "Another work showed that the antineoplastic drug 5-FU decreased the mRNA levels of Bcl-2 in the first 48 h, which coincided with the up-regulation of BAX, after 72 h of treatment Bcl-2 was up-regulated and the levels of BAX were decreased in human gastric adenocarcinoma." (PMID 26861394, 2016). "The study analysed the mRNA expression levels of ALB, BCL-2, NFKB1, HIF1A, and IL-6 in 408 stomach adenocarcinoma samples alongside non-tumour gastric tissues." (PMID 39816318, 2024). "In univariate analyses of AFP non-producing gastric adenocarcinoma group, lymph node metastasis, higher TNM stage and increased expression of Bcl-2 were found to be correlated with poor RFS and OS." (PMID 27057629, 2016).